TIPE3 (TNF alpha induced protein 8 like 3)
Diseases named in the same sentence as TIPE3 in open-access papers (continued):
Sharing a sentence is not in itself a finding about the gene and the disease.
tumor (continued). "Moreover, restoring TIPE3 expression significantly inhibited NPC cell proliferation, migration and invasion in vitro, and suppressed tumor growth and lung metastatic colonization in vivo, while silencing TIPE3 acted in an opposite way." (PMID 30217224, 2018). "Subcutaneous xenograft tumor experiment demonstrated that overexpressed TIPE3 could promote tumor formation in vivo." (PMID 28388580, 2017). "Hence, those data demonstrated that TIPE3 acted as a tumor suppressor gene in HNSCC." (PMID 37024453, 2023). "To determine whether TIPE3 restoration affected NPC tumor growth and lung metastatic colonization in vivo, we constructed xenografted tumor growth and lung metastatic colonization models by injecting SUNE1 cells stably overexpressing TIPE3 or vector into the dorsal flank or tail vein of nude mice." (PMID 30217224, 2018). "TIPE3 is predominantly found in the cytoplasm and membrane of tumor cells, while RAC1 is primarily located in the cytoplasm of tumor cells." (PMID 40904408, 2025). "In this study, we demonstrated that TIPE3 promotes autophagy in CRC cells and tumor-bearing mice via USP19/Beclin1 and induces macrophage M2 polarization, thus strengthening the resistance of tumor cells to L-OHP." (PMID 40280943, 2025). "First, we performed IHC staining of TIPE3 in the tumor tissues and adjacent normal tissues of 110 CRC specimens and found varying levels of the TIPE3 expression in both tissue types, with a high expression in the cytoplasm and low levels in the nucleus." (PMID 36755222, 2023). "On the contrary, knockdown of TIPE3 in MDA-MB-231 cells can significantly reduce the migration, invasion, and proliferation of tumor cells." (PMID 36755222, 2023). "To illustrate the potential tumor suppression mechanism of TIPE3 in HNSCC, we performed co-IP/MS to identify the proteins interacted with TIPE3 in Cal33 cells." (PMID 37024453, 2023). "Immunohistochemistry staining of TIPE3 and three prognostic immune biomarkers (CD8, CD20, and CD66b) was conducted in the tumor tissues and adjacent normal tissues." (PMID 36755222, 2023). "Xenograft tumors established with NSCLC cells overexpressing TIPE3 grew faster than those established with control NSCLC cells, leading to increases in tumor size and weight." (PMID 29510688, 2018). "To confirm the role and subcellular location of TIPE3 in the tumorigenesis of NSCLC, we established xenograft tumor models using nu/nu mice." (PMID 29510688, 2018). "In summary, TIPE3 regulated the expression of cell cycle- and apoptosis-related proteins through the USP19/Beclin1-pathway, thus reducing the damaging effects of L-OHP on tumor cells." (PMID 40280943, 2025). "Expression of TIPE3 and RAC1 in the blood samples of LUAD patients should also be explored, as blood samples could be easily accessed compared with tumor tissues." (PMID 40904408, 2025). "Tumor appearance, tumor volume, and tumor weight in mice showed that TIPE3 overexpression worsened tumor growth and that the therapeutic effect of L-OHP was weaker in OE-TIPE3 group than that in L-OHP group." (PMID 40280943, 2025). "Moreover, the combination of TIPE3 and RAC1 expression exhibited an optimal value in predicting tumor malignancy." (PMID 40904408, 2025). "Importantly, both TIPE3 expression and RAC1 expression were significantly increased in tumor tissues of patients with lymph node metastasis." (PMID 40904408, 2025). "All these results indicated that the TIPE3 and RAC1 promote tumor progression synergistically." (PMID 40904408, 2025). "Previous research found that TIPE3 may promote tumor progression via increasing the expression of RAC1, while other TIPE family members also interact with RAC1 directly during tumor progression." (PMID 40904408, 2025). "This body of research shows that TNFAIP8 and TIPE3 may act as oncogenes, while TIPE2 is likely a tumor suppressor gene." (PMID 36118167, 2022). "TIPE3 regulates PI3K/AKT signaling, and knocking down TIPE3 reduces tumor development in animals." (PMID 30586922, 2018).
tumor (continued). "Moreover, restoring TIPE3 expression suppressed NPC cell proliferation, migration and invasion in vitro, and inhibited tumor growth and lung metastatic colonization in vivo." (PMID 30217224, 2018). "TIPE3 overexpression in MCF-7 and MDA-MB-231 cells could promote tumor cell migration and invasion markedly." (PMID 28388580, 2017). "Therefore, the same signaling pathway may exist between TIPE3 and USP19 to achieve oncogenic effects, thereby enhancing the resistance of tumor cells to chemotherapy drugs." (PMID 40280943, 2025). "Notably, in xenograft tumor models established with NSCLC cells, stable overexpression of TIPE3 with C-terminal flag in NSCLC cells significantly promoted the tumor growth and enhanced the expression and plasma membrane localization of TIPE3 in tumor tissues." (PMID 29510688, 2018). "Furthermore, TIPE3 lacking the NT region appeared to exert a tumor suppression effect." (PMID 30217224, 2018). "The TIPE3 expression and the number of immune cells were scored, and the results showed that TIPE3 was significantly correlated with the number of CD20+ B cells in tumor tissues (p = 0.004), while no significant results were observed for the other markers." (PMID 36755222, 2023).
TIPE3 also shares sentences with these, for which no sentence is quoted: bladder cancer (2 papers); cervical cancer (2); colon cancer (2); prostate carcinoma (2); rectal cancer (2); breast tumor (1); cholangiocarcinoma (1); colorectal adenocarcinoma (1); head and neck cancer (1); head and neck squamous cell carcinoma (1); invasive breast carcinoma (1); malignant glioma (1); non-small cell lung carcinoma (1); ovarian carcinoma (1); ovarian tumors (1); sarcoma (1); stomach cancer (1).